TCERG1L (transcription elongation regulator 1 like)
Synonyms: FLJ38950
Tractability: PROTAC: ubiquitination databases record sites on it.
Gene: Protein-coding gene on chromosome 10 (131,092,391 to 131,311,736, reverse strand). Ensembl gene ENSG00000176769.
Subcellular location (Human Protein Atlas): Nucleoplasm; Cytosol
Gene Ontology:
Molecular function: transcription coregulator activity; RNA polymerase binding
Cellular component: nucleus
Genetic constraint (gnomAD): Loss-of-function variants: 38 observed, 43.38 expected, observed/expected ratio (o/e) 0.88, 90% interval 0.68 to 1.15. The synonymous counts are far from expectation, so gnomAD's model fits this gene poorly and the ratio says little. Missense variants: 769 observed, 628.74 expected, observed/expected ratio (o/e) 1.22, 90% interval 1.15 to 1.3. Synonymous variants: 316 observed, 259.89 expected, observed/expected ratio (o/e) 1.22, 90% interval 1.11 to 1.34.
Homologues: Orthologues: chimpanzee TCERG1L (99% identical), macaque TCERG1L (97% identical), dog TCERG1L (83% identical), pig TCERG1L (83% identical), rat Tcerg1l (81% identical), mouse Tcerg1l (81% identical), guinea pig TCERG1L (77% identical), tropical clawed frog tcerg1l (54% identical), zebrafish tcerg1l (48% identical). Paralogues in human: TCERG1 (34% identical), ARHGAP5 (15% identical).
Diseases named in the same sentence as TCERG1L in open-access papers:
TCERG1L is named in the same sentence as 21 diseases in open-access papers, as found by Europe PMC text mining. Sharing a sentence is not in itself a finding about the gene and the disease. The quoted sentences say what the papers report.
childhood cancer (2 papers, 2021 to 2022). "This recent study identified TCERG1L to be associated with ototoxicity in a relatively large European cohort of patients with childhood cancer and replication in similar cohorts." (PMID 36536332, 2022). "We found evidence that TCERG1L is related to direct cisplatin-induced hearing loss in childhood cancer patients, the results of which were strengthened through replication in two independent replication cohorts, and biological validation in vitro." (PMID 34262104, 2021). "In conclusion, the combined results of this study suggest that cisplatin-treated, non-cranial irradiated childhood cancer patients with a genetic intronic variant (rs893507) in TCERG1L have a 3.11 fold increased odds of developing cisplatin-induced hearing loss." (PMID 34262104, 2021).
Colon cancer (2 papers, 2014 to 2020). "We previously studied the promoter DNA methylation pattern of the TCERG1L gene, which is very frequently methylated in Colon cancer patients, in the blood samples of patients with CD to detect any disease-specific methylation." (PMID 32375395, 2020). "Hypermethylation of the TCERG1L promoter region leading to gene silencing has also been observed in colon cancer." (PMID 24499112, 2014).
Obesity (2 papers, 2017 to 2023). Accumulation of substantial excess body fat. "This site was found to be in proximity to the TCERG1L gene, which codes for a transcriptional elongation regulator that is a key regulator of human obesity." (PMID 37626570, 2023).
attention deficit-hyperactivity disorder (1 paper, 2015). A disorder characterized by a marked pattern of inattention and/or hyperactivity-impulsivity that is inconsistent with developmental level and clearly interferes with functioning in at least two settings (e.g. at home and at school). "Some have been associated with neurodevelopmental disorders: schizophrenia (DIXDC1, ARVCF, MAGI2, ZIC2), ADHD (attention deficit/hyperactivity disorder) (TCERG1L), movement disorders (NOL3, TP53INP2), Huntington’s disease (H2AFY2, AGPAT1), Parkinson’s disease (LMX1B), and autism (PLXNA4, WNT2)." (PMID 25748564, 2015).
colorectal cancer (1 paper, 2025). A primary or metastatic malignant neoplasm that affects the colon or rectum. "Additionally, the CpG site cg03943081 affects the methylation of the TCERG1L gene, with hypermethylation of TCERG1L being a potential biomarker for early detection of colorectal cancer." (PMID 40177272, 2025).
hearing loss (1 paper, 2021). "The TCERG1L gene, a paralog of TCERG1, is a transcription elongation regulator that has been described to be involved in the pathogenesis of cancer and non-cancer-related diseases, but it has not previously been associated with chemotherapy-induced hearing loss." (PMID 34262104, 2021).
Insulin resistance (1 paper, 2018). Increased resistance towards insulin, that is, diminished effectiveness of insulin in reducing blood glucose levels. "Variants in TCERG1L have been shown to be associated with fasting insulin and insulin resistance in an African–American population, which could have implications for growth of both the mother and the offspring." (PMID 28990592, 2018).
ulcerative colitis (1 paper, 2023). An inflammatory bowel disease involving the mucosal surface of the large intestine and rectum. "For instance, the hypermethylation of transcription elongation regulator 1-like (TCERG1L) is observed in precancerous colon polyps and has been regarded as a risk marker of CRC in patients with ulcerative colitis." (PMID 36869385, 2023).
cancer (3 papers, 2014 to 2021). A tumor composed of atypical neoplastic, often pleomorphic cells that invade other tissues. "Fibrillin 2 (FBN2) is an extracellular matrix protein, and the transcription elongation regulator 1-like (TCERG1L) gene is located on chromosome 10 and has recently been shown to have frequent cancer-specific methylation according to our microarray-based approaches." (PMID 33946400, 2021). "Using a genome-wide association study (GWAS) approach, we identified a genetic variant in TCERG1L (rs893507) to be associated with hearing loss in 390 non-cranial irradiated, cisplatin-treated children with cancer." (PMID 34262104, 2021). "Whilst expression in these cells may have been downregulated during immortalization, analogous to downregulation of this gene in cancer cells, the data suggest that any role TCERG1L may play in OM susceptibility is unlikely to occur through the innate inflammatory response to otopathogens." (PMID 24499112, 2014).
infection (1 paper, 2014). The state of being infected such as from the introduction of a foreign agent such as serum, vaccine, antigenic substance or organism. "In this study, we have also demonstrated that TCERG1L is expressed in adenoids but not in macrophage or epithelial cell lines, either with or without otopathogen infection." (PMID 24499112, 2014).
tumours (1 paper, 2020). "In all four tumours examined, a copy of TCERG1L was missing from this region." (PMID 32354058, 2020).
TCERG1L also shares sentences with these, for which no sentence is quoted: autism (1 paper); colon polyps (1); coronary artery disease (1); Crohn disease (1); diabetes (1); Huntington disease (1); movement disorder (1); neurodevelopmental disorder (1); Parkinson disease (1); schizophrenia (1).